IL6 (interleukin 6)
Diseases named in the same sentence as IL6 in open-access papers (continued):
Sharing a sentence is not in itself a finding about the gene and the disease.
endometriosis (continued). "IL-6 concentration is high in the uterine fluid of sows during embryo implantation, in preterm parturition in women, and in mares with endometritis and it is a marker of endometriosis in the uterine fluid of women." (PMID 36830341, 2023). "Additionally, IL-6 and TNFα facilitate adhesion of endometrial cells to the peritoneum, contributing to disease progression in endometriosis." (PMID 37834449, 2023). "Moreover, IL-1β enhances IL-6 and IL-8 production; they act synergistically to boost proliferation and decrease the apoptotic rate of endometriosis cells." (PMID 37447296, 2023). "In patients with endometriosis, the upregulation of miRNA 125b-5p and downregulation of let 7b-5p have been associated with increased proinflammatory cytokines such as TNF-α, IL-1β, and IL-6." (PMID 37834449, 2023). "In addition, inflammatory cytokines such as TNF-α and IL-6 activate c-jun terminal kinases (JNK) in the endometrial cells of endometriosis patients." (PMID 37033937, 2023). "Furthermore, IL-6 promotes inflammation and facilitates the occurrence and development of endometriosis." (PMID 36865552, 2023). "At the phyla level, a higher abundance of Proteobacteria in peritoneal fluid could be seen among infertile patients with endometriosis, in which several inflammatory factors, including IL-6, IL-10, IL-13, and TNF-α, may be involved." (PMID 37764164, 2023). "IL-6 and IL-8 are also increased in the peritoneal fluid of endometriosis patients." (PMID 37893241, 2023). "However, this action contributes to the inflammatory profile observed in patients with endometriosis through the secretion of IL-6 and IL-1β by these cells." (PMID 35807280, 2022). "Elevated IL6 secretion in blood and ascites is high in endometriosis." (PMID 35565252, 2022). "Hence, inflammatory mediators such as IL‐1β, IL‐6, IL‐8 increase in the peritoneal, serum, and endometrium of endometriosis patients, leading to enhancing proliferation and decreasing apoptotic rate in endometriotic cells." (PMID 36266431, 2022). "In this way, increased levels of TNF-α, IL-6, IL-8, IL-10, VEGF, and MCP-1/CCL2, as well as different metalloproteinases (MMPs), are associated with the establishment and progression of endometriosis." (PMID 35164046, 2022). "Recent comprehensive analyses have shown that pathological mutations in cancer-related genes such as KRAS and PIK3CA are frequently observed in endometriosis, and these oncogenic abnormalities may lead to high expression of TF and IL6 in endometriosis." (PMID 35565252, 2022). "Numerous mechanisms are involved in endometriosis-related pain such as various algogens (pain-producing agents), cytokines (such as IL-1b, IL-6, and TNF-a), growth factors (such as b-nerve growth factor and vascular endothelial growth factor), and several chemokines, such as CCL243,44." (PMID 36266431, 2022). "Endometriosis patients also display increased IL-1β, IL-6, and TNFα." (PMID 36532015, 2022). "A proinflammatory cytokine IL-6 is elevated in the peritoneal fluid and serum of women with endometriosis and induces prolonged activation of STAT3 via association with the IL-6 receptor to enhance endometriosis progression." (PMID 36358904, 2022). "For instance, there is increased expression of immunoglobulins IgM, IgA, and IgG in patients with chronic endometritis (CE) and RIF, and significantly higher levels of the proinflammatory cytokines interleukin 6 (IL-6), proIL-1β, and IL-1β occur among patients with endometriosis." (PMID 35008911, 2022). "In addition, the cytokines IL-1α, IL-6, IL-8, IL-18, and TNFα have been found to increase in endometriosis consistently." (PMID 35628423, 2022). "Notably, the IL-6 and IL-8 concentrations in the serum of patients with endometriosis are higher than those in healthy women." (PMID 36093086, 2022).
endometriosis (continued). "Previous studies have shown that consumption of legumes reduces inflammatory markers such as CRP, TNF-α, IL-6, and other adhesion molecules, as well as the levels of adiponectin that may provide a mechanistic role of legumes in endometriosis." (PMID 36138433, 2022). "Moreover, the dysregulation of the IL6/STAT3 signaling pathway in endometriosis can also be induced under hypoxia conditions and in the presence of inflammatory cytokines such as TNFA, contributing to the establishment of ectopic tissue." (PMID 36232817, 2022). "IL-6 levels decrease after surgery or GnRH agonists are used to treat endometriosis." (PMID 36532015, 2022). "Elevated serum levels of IL-6 are considered biological markers for the diagnosis of endometriosis." (PMID 35807280, 2022). "Elevated plasma levels of IL-6 and G-CSF have both been reported in endometriosis patients." (PMID 36016927, 2022). "Additionally, endometriosis patients are found to have elevated levels of proinflammatory factors such as IL-6, IL-8, TNF-α, and prostaglandin E2." (PMID 36361745, 2022). "There is evidence that IL-6 expression may be induced by endometriosis inflammation, and long-term exposure of ovarian surface epithelial cells to IL-6-rich endometrioma fluid can induce the expression of gene expression patterns typical of OCCC." (PMID 35062908, 2022). "IL‐6 is a crucial mediator of cytokine cascade in endometriosis." (PMID 33325132, 2021). "Importantly, miR-125b has been observed to affect the levels of TNF-α, IL-6, and IL-1β, which belong to the group of inflammatory cytokines, and their concentration is elevated in women with endometriosis." (PMID 34201813, 2021). "In endometriotic cells (ECs) in endometriosis stage IV, the increased levels of IL-6 showed a dependence on the number of cells, which may explain the high proliferative rate of these cells if we consider the role of this cytokine in cancer." (PMID 33435569, 2021). "Therefore, it would be interesting to have data on IL-6 levels under estrogens treatment in endometriosis." (PMID 33435569, 2021). "This disruption in interaction may also be true in endometriosis, since we and others have shown that IL-6 is increased in patients with endometriosis." (PMID 33800594, 2021). "Based on the analysis of the top gene targets in the PPI network, we found that WJD might treat endometriosis by regulating inflammation and/or the endocrine system through IL6, ERα, and other cytokines." (PMID 34257679, 2021). "By contrast, those ligands may be less present in the hEMSC niche, as excess PPAR-γ activation, through its subsequent stimulation of IL-6, can contribute to the onset of endometriosis in the female reproductive system." (PMID 34112245, 2021). "IL-6 is the most studied pro-inflammatory cytokine in endometriosis." (PMID 34639133, 2021). "IL-6 or peritoneal fluid from endometriosis patients reduces the cytolytic activity of NK cells, concomitantly with the down-regulation of granzyme B, perforin, and the killer activating receptor (NKp46), while increasing the killer inhibitory receptor (CD158b)." (PMID 34531861, 2021). "Women with endometriosis had increased concentrations of IL-6 and IL-10." (PMID 34360900, 2021). "In this study, IL-3, IL-5, and IL-6 were measured in the FF of women with endometriosis." (PMID 35571503, 2021). "Moreover, elevated serum levels of tumor necrosis factor-alpha (TNF-α), interleukin-1 (IL-1), and interleukin-6 (IL-6) have been found, by some authors, in females with endometriosis." (PMID 34754275, 2021). "Moreover, macrophages responses to estradiol in the PF of women with endometriosis occurred via in vivo of secrete interleukin-6 and tumor necrosis factor-α." (PMID 33980258, 2021).
endometriosis (continued). "In summary, the results demonstrated a significant elevation in the IL-6 concentration and a remarkable reduction in the IL-3 levels in the FF samples of women with endometriosis compared to the control group, suggesting the involvement of these cytokines in the pathogenesis of endometriosis." (PMID 35571503, 2021). "IL-3 and IL-6 were significantly changed in the FF of the women with endometriosis compared with the control group (p = 0.04, and p < 0.01, respectively), and the mean concentration of IL-5 in the endometriosis group was lower than in the control group (p = 0.5), but this was not significant." (PMID 35571503, 2021). "In addition, studies suggest that IL-6 is upregulated in endometriosis patients, which leads to downstream signaling of pSTAT3 and BCL6." (PMID 34698105, 2021). "Elevated IL-6 serum levels are also observed in endometriosis." (PMID 34573967, 2021). "Many authors reported high levels of pro-inflammatory cytokines (e.g., IL-1β and IL-6 in pelvic fluid in women with endometriosis compared to the control group), which indicates a significant role for immune markers in the pathogenesis of endometriosis." (PMID 33669013, 2021). "Others factors, like estrogen receptor (ER) alpha, ERbeta, CD68, NCL-MACRO, and HAM56 and inflammatory cytokines IL-1beta, TNF-alpha, and IL-6, as well as pro-inflammatory transcription factor NF-κB are upregulated in macrophages from peritoneal fluid in patients with endometriosis." (PMID 32751735, 2020). "Endometriosis is considered an inflammatory disease, due to increased levels of activated macrophages and cytokines such as interleukins (IL-6, IL-8, IIL-1β), tumor necrosis factor-alpha (TNF-α), and macrophage migration inhibitory factor (MIF), in the peritoneal fluid of affected women." (PMID 32143439, 2020). "For example, our group has previously demonstrated that miR-142-3p targets STS and interleukin-6-coreceptor gp130 in endometrial stroma cells indicating a possible relevance for dysregulation of the endocrine milieu and chronic inflammation in endometriosis." (PMID 32824678, 2020). "The levels of IL-4 and IL-6 are increased remarkably in women with endometriosis." (PMID 32145751, 2020). "The peritoneal fluid of women with endometriosis has increased IL-6 levels." (PMID 32552749, 2020). "Diels extract can be developed for the treatment of endometriosis by inhibiting inflammatory reactions and could significantly decrease NF-kB/β-actin and IL-6/β-actin mRNA expression in the uterus of rats with pelvic inflammation." (PMID 33328985, 2020). "Let-7b treatment of endometriosis could decrease inflammatory signaling (IL-6), decreased estrogen signaling (ER and Cyp19A1), and also decrease KRAS." (PMID 32850438, 2020). "Serum concentration of IL-6 was analyzed along with the concentration of surface antigen CA125, used frequently as a marker of disease, and both showed an association to moderate-severe endometriosis." (PMID 32063886, 2019). "There is some research showing that the expression of BAFF, TNF-α or IL-6 may be affected in case of endometriosis." (PMID 31088412, 2019). "In rats, increased serum IL‐6 levels after surgical induction of endometriosis suggest that IL‐6 may be involved in the initial development of endometriosis." (PMID 30828987, 2019). "The NF-κB system dysfunction indicated by the molecular alterations of IL-6 and RelA (p65) during the late secretory phase in eutopic endometrium from endometriosis patients suggested that NF-κB could be an important factor in endometriosis etiology." (PMID 29871974, 2018). "For example, endometriosis may impair sperm mobilization through macrophage-secreted IL-1, IL-6, and macrophage migration inhibitory factor (MIF)." (PMID 30104541, 2018). "Neutralization of IL-6 diminished macrophage M2 polarization in endometriosis." (PMID 30276219, 2018).
endometriosis (continued). "Taken together, these findings indicate that IL-6 may mediate important biological events that contribute to the initiation as well as progression of endometriosis." (PMID 30276219, 2018). "Moreover, the IL-4 and IL-6 expression exhibited an increase in endometriosis compared to that in control group (P < .05)." (PMID 29901577, 2018). "We show that IL-6 as well as other inflammatory mediators are higher in women with endometriosis." (PMID 28754906, 2017). "Recently, IL-6 in the PF of endometriosis patients has been identified as a possible immunosuppressant of NK cell cytotoxicity, and it may play a crucial role in impairing NK cell function by regulating SHP-2 expression." (PMID 27294113, 2016). "IL-6 also seems to increase in concentration in more advanced stages of endometriosis." (PMID 26247027, 2015). "The high levels of IL-6 could be produced by the increased number of macrophages that infiltrate the peritoneal cavity in endometriosis." (PMID 26247027, 2015). "We can speculate that increased levels of oxidized LDL in the peritoneal cavity of women with severe endometriosis may be one of the factors responsible for increased levels of M-CSF, IL-6, and TNF-α in PF." (PMID 23861560, 2013). "In this group only in one case we have confirmed endometriosis, and IL-6 may be produced locally within foci of endometriosis." (PMID 24298555, 2013). "Endometriosis is an aseptic inflammatory process accompanied by altered immune-related cell functions such as accumulation of macrophages and increased expression of growth factors, cytokines and specifically interleukins IL-1 and IL-6." (PMID 23638035, 2013). "IL-6 is a potent multifunctional protein, which promotes endometrial cell proliferation and angiogenesis; its secretion is elevated in ectopic endometrial tissue and its concentrations are high in peritoneal fluid of patients with endometriosis." (PMID 23766765, 2013). "This alone may be important in biologic settings such as pelvic inflammation and endometriosis where IL-6 levels are elevated." (PMID 22536401, 2012). "Other than peritoneal fluid, follicular environment in endometriosis demonstrates higher IL-6 which may hamper oocyte quality prior to ovulation." (PMID 22536401, 2012). "Considering the family of interleukins, patients with endometriosis have higher levels of IL-6." (PMID 23093966, 2012). "Alternatively, increased IL-6 has been demonstrated in the endometrium of women with endometriosis." (PMID 17118173, 2006). "Although DCs do not directly contribute to the pain associated with endometriosis, they may do so indirectly by secreting cytokines that support lesion survival, such as IL-10, and pro-inflammatory cytokines like IL-1β and IL-6, which promote neurogenesis." (PMID 40747182, 2025). "Additionally, gut-derived LPS from Gram-negative bacteria such as E. coli activates Toll-like receptor 4 (TLR4), triggering the increased production of pro-inflammatory cytokines including TNF-α, IL-6, and IL-1β—all of which are elevated in the peritoneal fluid of individuals with endometriosis." (PMID 40430189, 2025). "Therefore, it is hypothesized that combining IL-6 and IL-8 with serum carcinogenic antigen-125 levels, a major biomarker of endometriosis, could predict infertility in patients with endometriosis." (PMID 40130159, 2025). "IL-6 is another major cytokine that has been found at elevated concentrations both systemically and in peritoneal fluid of ES patients, where it is secreted by both migrated macrophages in the endometriosis lesion environment and (to a minor part) the endometrial cells." (PMID 40747097, 2025). "Research demonstrates that IL-6, in conjunction with other cytokines, cultivates a peritoneal milieu favorable for the implantation and proliferation of endometriotic cells, underscoring its importance in endometriosis and various inflammatory and autoimmune disorders." (PMID 40938862, 2025).
endometriosis (continued). "IL-6 inhibition has been considered as a therapeutic approach to peritoneal dialysis-related fibrosis and endometriosis, for example, and might yield benefit in palliating the debilitating digestive, nutritional and cachectic consequences of PC beyond any direct anti-neoplastic activity." (PMID 38689325, 2024). "Numerous studies have shown increased concentrations of interleukins (IL-1, IL-6, IL-8, and IL-33), tumor necrosis factor-alpha, insulin-like growth factor 1, and vascular endothelial growth factor in endometriosis patients, among endometriosis lesions and peritoneal fluid." (PMID 39136014, 2024). "Therefore, the synergistic action of ARID1A loss and PI3K/AKT/mTOR pathway upregulation in the malignant progression of endometriosis can be partially explained by their cooperation in activating IL-6 and thus in promoting a pro-tumorigenic inflammatory cytokine signaling." (PMID 37627318, 2023). "Interleukin-6 (IL-6), a key cytokine involved in inflammation, was found in lower levels in the dienogest group, hence showing that this treatment lowers the inflammatory response during the perioperative period and other endometriosis-related inflammatory reactions." (PMID 37959232, 2023). "Besides, this result could lead to IL-6 being a good biomarker for endometriosis in symptomatic patients with pelvic pain or subfertility." (PMID 36902616, 2023). "Also, higher consumption of fruits and green vegetables may be protective because it can decrease inflammatory markers such as interleukin-6 (IL-6) that are elevated among women diagnosed with endometriosis." (PMID 36138433, 2022). "Proinflammatory cytokines such as TNF-α, IL-1β, IL-6, and IFN-γ initiate and amplify inflammatory and immune responses by signaling the recruitment of additional proinflammatory mediators and immune cells to the site of injury and have been implicated in endometriosis development and progression." (PMID 35409294, 2022). "Moreover, OCCC specifically shows high expression of tissue factor and interleukin-6, which play a critical role in cancer-associated hypercoagulation and may be induced by OCCC-specific genetic alterations or the endometriosis-related tumor microenvironment." (PMID 35565252, 2022). "The altered local expression of IL-6 may be important in the pathogenesis of endometriosis." (PMID 35805112, 2022). "Together with significantly lower IL-6 concentrations in healthy subjects compared to both endometriosis groups, this may suggest that interleukin 6 concentration slowly increases from the beginning of the disease (early stages) and reaches the maximum level when endometriosis is regarded as severe." (PMID 33669013, 2021). "IL-6 is related to: monocyte recruitment, in vitro polarization of pMφ to the M2 phenotype, the number of lesions generated in a murine model of endometriosis, and together with its receptor (IL-6R), has been implicated in endometrial stromal cells (ESC) growth regulatory signaling in vitro." (PMID 34639133, 2021). "So IL‐6 might be one of the cytokines involved in the pathogenesis of endometriosis." (PMID 33325132, 2021). "However, other studies in agreement with present study results reported that the predictive value of IL-6 is low and cannot be used as a suitable diagnostic or prognostic test for endometriosis." (PMID 35571503, 2021). "Endometriosis is known to be associated with a plethora of various proinflammatory and immunoregulatory cytokines, and in the present study we confirmed that the peritoneal fluid of women with this disease contains increased concentrations of TGF-β1/2, IL-6, and IL-10." (PMID 34501240, 2021). "A rodent model of endometriosis revealed that treatment with candidate miRNA, let-7b resulted in a decrease in endometriotic lesion size and decreased expression of several genes important in the pathophysiology of endometriosis including Esr1, Esr2, CYP19a, and IL-6." (PMID 34244742, 2021).